CTLA4 (cytotoxic T-lymphocyte associated protein 4)
Diseases named in the same sentence as CTLA4 in open-access papers (continued):
Sharing a sentence is not in itself a finding about the gene and the disease.
tumor (continued). "Furthermore, when combined with anti‐CTLA‐4 antibodies, significant inhibition of tumor metastasis and recurrence was realized." (PMID 32328428, 2020). "We next tested whether the tumor-reactive potential of TILs was affected by the addition of anti-CTLA-4 antibody during TIL culture." (PMID 32127601, 2020). "Moreover, combining bicarbonate therapy with anti-PD-1 or anti-CTLA-4 checkpoint blockade or ACT improved tumor regression in comparison to either treatment alone in murine cancer models." (PMID 33324565, 2020). "However, treatment significantly reduced activated Tregs in the tumor microenvironment: Foxp3+CTLA4+ CD4+ Tregs were reduced in all patients, from 11.8% to 2.9%, p = 0.0067." (PMID 32681091, 2020). "Anti-tumor activity via checkpoint blockade, such as with a CTLA4 blocking antibody, was initially observed in syngeneic models, suggesting that syngeneic model findings may translate to the clinic." (PMID 31898484, 2020). "Similarly, intratumoral cGAMP injection results in a dose-dependent inhibition of subcutaneous B16 tumor growth when combined with anti-CTLA4 and anti-PD-1 mAb treatment." (PMID 32774773, 2020). "Second, considering the mechanism of tumor immunity, the correlation between the expression of markers such as PD-L1, PD-1 or CTLA-4 and the expression level of UL111A protein may require further study." (PMID 32025866, 2020). "In conclusion, this evidence suggests an important role of intratumoral macrophages-expressing PD-L1 and other immunosuppressing molecules in the response to PD-1 and CTLA-4 blockade, thereby inhibiting the induction of proliferation and reactivation of tumor-reactive T cells." (PMID 32071302, 2020). "CTLA-4-mediated Treg depletion increases the Teff/Treg ratio within the tumor microenvironment and is associated with enhanced effector phenotypes of CD8 and CD4 cells in the tumor microenvironment." (PMID 32467593, 2020). "Nonetheless, CD44+ CD8 T cells were found in MOC1 tumor tissues one week after combination of CD44-targeted NIR-PIT and CTLA4 mAb, which suggested that newly induced T cells were accommodated and operated anti-tumor immune activity to suppress tumor growth for MOC1 tumors." (PMID 32937841, 2020). "Thus, PD-1 and CTLA4 play important roles in tumorigenesis and tumor immunity and can serve as prognostic biomarkers in different cancer types." (PMID 33072070, 2020). "Interestingly, adding the CTLA-4 blocking antibody in the initial phase of the TIL culture resulted in more potent anti-tumor TILs in comparison to standard TIL cultures." (PMID 32127601, 2020). "A few MSS tumours also had increased fractions of CTLA-4+ T cyt cells." (PMID 33228141, 2020). "Although CHI (including PDCD1 blockade or anti-CTLA4) in patients with dMMR/MSI-H mCRC significantly increase the antitumor activity of tumor specific CD8+ T-cells with highly durable tumor response, they are associated with virtually no activity in patients with pMMR/non-MSI-H mCRC." (PMID 33240813, 2020). "Notably, the addition of the PI3K-γ inhibitor to the combination of anti-CTLA-4 plus anti-PD-1 induced a complete remission in 80% of B16-GM-CSF tumor-bearing mice." (PMID 33212945, 2020). "Interestingly, ID-1 showed a higher binding affinity than Ipilimumab for the CTLA-4 positive tumor cells." (PMID 32781690, 2020). "Additionally, anti-PD-L1/CTLA-4 nanobody-secreting CAR T cells have demonstrated enhanced anti-tumor response in vivo and indicate synergistic potential." (PMID 32793488, 2020). "Additionally, it was found that the lysate of L. acidophilus promoted the anti-tumor effects of CTLA-4 by reducing the quantity of Treg as well as M2 cells, while increasing the levels of T cells and IFN-γ, Granzyme B, and TNF-α." (PMID 33318319, 2020).
tumor (continued). "In vivo anti-CTLA-4 treatment increases the frequency of neo-antigen specific tumor-infiltrating T cells in other responsive murine cancer lines, suggesting that clonal expansion of T cells, and reduction in tumor TCR diversity is a feature that accompanies anti-CTLA-4 treatment." (PMID 33163002, 2020). "This is especially true for anti-CTLA-4 in which any increase in T-cells could lead to attacks on normal tissues; anti-PD-1/PD-L1 are basically tumor specific in their action." (PMID 32640548, 2020). "Finally, we tested for potential therapeutic anti-tumor effects of endogenous anti-tumor antibodies in the serum of mice rendered disease-free by RT + IT-IC + anti-CTLA-4 treatment of a B78 tumor." (PMID 32849544, 2020). "Furthermore, the immune checkpoint proteins on tumour cells, PD-1 and CTLA-4, suppress T cell metabolism." (PMID 33092283, 2020). "Therefore, CTLA-4 recognizes B7 ligands on the surface of tumor cells and further inhibits T cell activation." (PMID 32522267, 2020). "Notably, it was recently shown that treatment of mice with tumor necrosis factor (TNF) inhibitors concomitantly with anti-PD-1 and anti-CTLA-4 antibodies ameliorates immune-related colitis and, in addition, improves anti-tumor efficacy." (PMID 31947592, 2020). "Although Bcl6 deletion alone greatly improved the therapeutic efficacy, the combination of Bcl6 deletion and anti-CTLA4 or anti-PD1 did exhibit additional effects at delaying tumor growth, indicating that Bcl6 can be a potential therapeutic target combined with ICB in cancer immunotherapy." (PMID 32477338, 2020). "Previous studies using DNMTis to increase the immunogenicity of tumor cells have reported a concomitant increase in the expression of immune checkpoint proteins, such as CTLA-4 and/or PD-L1 on the surface of treated cells, necessitating combination treatment with checkpoint immunotherapy." (PMID 32296439, 2020). "Recently, immune checkpoint inhibitors, including CTLA-4 and programmed cell death protein 1 (PD-1)/programmed cell death 1 ligand 1 (PD-L1) inhibitors, which reverse the signals from the immunosuppressive tumor microenvironment (TME), are being investigated as potential treatment modalities." (PMID 33123161, 2020). "However, many types of tumor cells can upregulate CTLA-4 in the tumor microenvironment, allowing these cells to evade targeting and destruction by the body’s immune system by prematurely inhibiting T cells." (PMID 32944086, 2020). "Cancer immunotherapy reactivates the immune function of immune cells by blocking immune checkpoints (e.g., programmed death receptor 1/programmed death ligand 1 (PD-1/PD-L1), cytotoxic T lymphocyte antigen 4 (CTLA-4)) and restores the anti-tumor activity of immune cells." (PMID 32522267, 2020). "Indeed, comparing the tumors that developed on the left and right flanks on each recipient mouse, we found their tumor size to be significantly positively correlated, especially in the anti-PD-1- and anti-CTLA-4-treated groups." (PMID 33059736, 2020). "Further statistical analysis showed that higher serum CTLA-4 levels are associated with small tumor size (P < 0.001), absence of tumor necrosis (P < 0.001), and non-basal status (P = 0.002)." (PMID 32123292, 2020). "The magnitude and the breadth of stimulatory molecules in comparison to inhibitory counterparts, as exemplified here by a balance of CD28 and CTLA-4-derived signals, is critical to T cell activation and tolerance, and represents a window of opportunity for clonal selection during tumor evolution." (PMID 32117295, 2020). "While a cytotoxic T lymphocyte antigen-4 (CTLA-4) blockade strategy was applied into mice with breast cancer or lung cancer after the tumor ablation by PTT, the antitumor efficacy was much promoted leading to effective rejection of secondary tumors and minimized tumor metastasis." (PMID 32528941, 2020).
tumor (continued). "It has been found that combining anti-CTLA-4 antibodies with immunotherapy, chemotherapy or radiotherapy has a great influence to ameliorate long-term survival rates of patients with various types of tumor malignancies." (PMID 33519807, 2020). "Checkpoint inhibitor therapy targeted at immune cells associated with checkpoint proteins, like PD-L1, PD-L2, B7-H3, and CTLA-4, could help disinhibit the host immune system to help combat tumor survival and growth." (PMID 32982948, 2020). "Indeed, IDO-deficient mice increase CD4+ and CD8+ effector T cell infiltration in the tumor microenvironment and show better anti-CTLA-4 therapy effects than that of the wild-type." (PMID 31968651, 2020). "Together, these observations suggest that CTLA-4 blockade in tumor cells may contribute to generating a favorable microenvironment for immune responses." (PMID 32850353, 2020). "Furthermore, immunohistochemistry staining for CD3+ T cells in the MC38 tumor model revealed the highest CD3+ T-cell tumor infiltration in the anti-CTLA-4/PD-1 monoclonal antibodies combination setting." (PMID 33585182, 2020). "In addition, SPSZ combined with anti-CTLA-4 effectively inhibited tumor growth through the synergistic effect of PDT and immunotherapy." (PMID 33240857, 2020). "In order to further explore the relationship between HDACi resistance and immune checkpoint regulation, we measured the expression levels of mRNAs encoding the immune checkpoint molecules PD-L1, CTLA4, B7-1, B7-H3, B7x, VISTA, and Galectin-9, in both SAHA-responsive and -resistant tumor tissues." (PMID 32934224, 2020). "The inhibitory receptors PD-1 and CTLA-4 displayed elevated expression on the CD39+ subset, supporting the previous scRNA-seq data, which identified higher expression of genes associated with exhaustion on tumor-infiltrating CD39+ MAIT cells, such as CTLA4 or HAVCR2." (PMID 33205061, 2020). "Interestingly, a small subset of genes enriched in tumor Treg cells such as CTLA4, TIGIT, TNFRSF9, CD27, and LAYN are also highly expressed by exhausted tumor‐infiltrating CD8+ T cells reflecting a shared program of activation and exhaustion in these cells." (PMID 32272497, 2020). "Furthermore, tumor cells limit antitumor responses via immune checkpoints such as CTLA-4 and PD-1 moleculars." (PMID 32221812, 2020). "Previous studies have shown that TMB could predict patients’ survival in diverse tumor types with either anti-CTLA-4 or anti-PD-1 treatment." (PMID 33585244, 2020). "Hence preclinical models have been widely used to study the effects of anti-CTLA-4 on tumor TCR repertoires." (PMID 33163002, 2020). "Negative regulators of the immune response (PD-L1, CTLA4, etc.)might be involved in counteraction of anti-tumor immune response." (PMID 33680932, 2020). "T lymphocytes express inhibiting receptors involved in tolerance regulation against self-antigens, such as CTLA-4 (Cytotoxic T Lymphocyte Antigen–4) and PD-1 (Programmed Death–1), which are used by tumor cells to create an immunosuppressive state and escape of the immune system." (PMID 32580514, 2020). "Indeed, our results revealed that most tumor samples scored as FoxP3-positive in interstitial lymphocytes (74%), suggesting Treg tumor infiltration, and strongly correlated with interstitial CTLA-4 expression." (PMID 32123292, 2020). "Moreover, inhibition of the CTLA-4/B7 signal in lymph nodes increases activated CD8+ cells which will subsequently infiltrate the tumor and be part of the microenvironment." (PMID 33086471, 2020). "dMMR/MSI-H tumors are also largely infiltrated by immune cells, in particular CD8+ and T-helper 1 (Th1) CD4+ lymphocytes expressing high levels of CTLA-4 and PD-1, whereas myeloid cells expressing the immune checkpoint ligands (PD-L1) are mainly located at the tumor-stroma interface." (PMID 32962159, 2020).
tumor (continued). "Based on the AKT pathway, tumors were categorized as: CTLA-4H/H−AKT (N = 156), which do not express membrane CTLA-4, and CTLA-4H/L−AKT, representing our study phenotype where CTLA-4 is up-regulated in tumor cells and is activated-like, as defined by the down-modulation of the AKT pathway." (PMID 32850353, 2020). "Taken together, these results suggest that tumor cells over-expressing CTLA-4 may show distinct clinical and therapy responses as a result of the established biological signaling pathways." (PMID 32850353, 2020). "Furthermore, azacytidine and CTLA-4 mAb combination therapy represses tumor growth more strongly than each of the monotherapies, via the upregulation of MHC class I components as the putative mechanism." (PMID 31968651, 2020). "Altogether, the disparate effects of tumor CTLA-4 expression make a strong case for studying the effects of CTLA-4 expression within each separate microenvironment in each cancer type and at different stages of cancer progression, rather than extrapolating results from one cancer type." (PMID 33384695, 2020). "In the tumor microenvironment, exhausted T-cells are determined by impaired functional activities like cytokines secretion and up-regulation of co-inhibitory molecules, including CTLA-4, PD-1, Tim-3, and LAG-3." (PMID 32986360, 2020). "However, the addition of anti-PD-1 and anti-CTLA-4 antibodies to shIDO-ST treatment (shIDO-ST + ICB) resulted in significant tumor control compared to shScr-ST + IgG or shIDO-ST + IgG as well as shScr-ST + ICB." (PMID 33339195, 2020). "We recently found that it is expressed also on tumor and NK cells, suggesting other possible unknown roles of CTLA-4." (PMID 32781690, 2020). "For anti-CTLA-4 Ipilimumab, the predictive value of tumor biomarkers remains to be consolidated." (PMID 32793228, 2020). "Particularly, CTLA-4 and PD-1 inhibitors can stimulate anti-tumor immune responses." (PMID 32847045, 2020). "Thus, the antibodies blocking CTLA-4 and PD-1 and its ligand PD-L1 show promising anti-tumor effects in a wide range of tumor types by priming T cells against tumor antigens." (PMID 32244946, 2020). "Given the potent antitumor efficacy of our RT + IT-IC + anti-CTLA-4 in situ vaccine regimen, we hypothesized that such a powerful immune provoking therapy might also be priming a humoral anti-tumor response." (PMID 32849544, 2020). "The ligand of CTLA-4, B7, is a protein expressed on activated antigen presenting cells, while for PD-1 it is the programmed death 1 ligand (PD-L1), found on a variety of immune cells, as well as expressed in several tumor types." (PMID 32640548, 2020). "Immune checkpoints, such as programmed cell death protein 1 (PD1) and its ligand-PDL-1, as well as cytotoxic T-lymphocyte-associated protein 4 (CTLA-4) inhibitors, exhibit antitumor effects by altering the interaction between the immune system cells and tumor cells." (PMID 32751138, 2020). "At present, CTLA‐4 and PD‐L1 are the two important routes for tumor immune escape." (PMID 33204848, 2020). "In order to overcome limitations created by the PD-L1/PD-1 interaction and to reduce the rate of tumor recurrence in these tumors, an immune-based treatment approach targeting PD-1 and CTLA-4 on immune cells and PD-L1 on tumor cells may be beneficial." (PMID 32090113, 2020). "The blocking of CTLA-4 thus leads to the lifting of this “brake” and allows the T-cells to proliferate and become activated when they encounter a dendritic cell (DC) presenting a tumor antigen within a tissue." (PMID 32443877, 2020). "Also, combination of PD-1/CTLA-4 blockade and depletion of Tregs in anti-tumor therapy have been shown to be effective." (PMID 32240238, 2020). "Combined use of anti-PD-1 and anti-CTLA-4 can effectively prevent tumor growth." (PMID 33679686, 2020).
tumor (continued). "Indeed, tumor gene expression signatures from many anti‐CTLA‐4/anti‐PD‐1 non‐responders indicate that other co‐inhibitory receptors should also be evaluated when considering optimal combinatorial checkpoint blockade strategies." (PMID 32508018, 2020). "Clinical trials with CTLA-4 inhibitors have shown durable tumor responses in multiple cancer types." (PMID 33061969, 2020). "We described that CTLA-4 might regulate tumor immune microenvironment by enhancing relevant immunomodulators, such as IL-15 and CSF-1, which prime NK and M1 macrophages, two cells interconnected by their immunomodulatory functions." (PMID 32850353, 2020). "In particular, the anti-tumor effects observed after monoclonal antibody (mAb)-mediated the blockade of the ICPs; cytotoxic T lymphocyte associated protein-4 (CTLA-4, CD152), programmed death-1 (PD-1, CD279) and its ligand PD-L1 (CD274, B7-H1), revolutionized the field of immuno-oncology." (PMID 33374804, 2020). "Under the treatment of ionizing radiation combined with an-CTLA-4 therapy, Shane’s group found that STING absence prevented abscopal tumor regression, and deficient STING significantly impaired CD8+ T cell infiltration in the tumor tissues." (PMID 32571374, 2020). "Indeed, it was recently reported that TGF‐β‐driven CD80 expression on tumor‐initiating stem cells promotes resistance to adoptive cell transfer (ACT) therapy via a CTLA‐4‐dependent mechanism." (PMID 32508018, 2020). "CTLA-4 integrates with the costimulatory molecules CD80 (B7-1) and CD86 (B7-2) that express on the surfaces of APCs, while PD-L1 is expressed on a wide variety of cell types, including tumor-associated fibroblasts, tumor cells, APCs, etc.." (PMID 30774597, 2019). "In RCC, about 1% of TIMC express CTLA-4, and expression increases with higher tumor stages." (PMID 31137694, 2019). "Co-blocking CTLA-4 and PD-1 led to synergistic anti-tumor effects." (PMID 31156651, 2019). "However, when tumor bearing mice are treated with anti-CTLA-4 monoclonal antibodies, mimicking the clinical ipilimumab therapy, improved control of tumor growth is only seen in conjunction with adoptive transfer of F5 T cells." (PMID 31249570, 2019). "ICB therapy based on CTLA-4 inhibition led to tumor regression in animal models." (PMID 30621125, 2019). "Thus, NICs cross the BBB, allowing conjugated mAbs to bind to CTLA-4 and PD-1 and modulate the immune response in the tumor area." (PMID 31462642, 2019). "Combination with ipilimumab and nivolumab may further enhance immune stimulation by preventing immune silencing effects including Treg activation or CTLA-4 and PD-1 expression on tumor and immune cells." (PMID 31192129, 2019). "As starting tumour size increases, the tumours progressively grow with anti-CTLA-4 monotherapy, while in response to anti-PD-L1 monotherapy and combination therapy tumours with initial size of 35 mm and smaller regress, whereas tumours with initial size above 40 mm grow." (PMID 31218069, 2019). "However, another study showed an anti-tumor effect for a monovalent anti-CTLA-4 nanobody in a similar B16 mice model." (PMID 31544819, 2019). "Classical tumor immune checkpoints include PD-1, PD-L1, PD-L2 and CTLA-4." (PMID 31419958, 2019). "Based on this knowledge, Allison’s group proposed that the blockade of CTLA-4 could boost the amplitude of CD8+ T cell activation thereby achieving a better CD8+ T cell-mediated tumour eradication." (PMID 31331034, 2019). "Checkpoint inhibition therapy involves the use of specific monoclonal antibodies, namely, anti-CTLA-4, anti-PD-1, and anti-PD-L1 antibodies, which bind to the immune checkpoint proteins of T cells to remove the inhibition of T cell function by tumor cells." (PMID 31443694, 2019).